PAK1 (p21 (RAC1) activated kinase 1)
Diseases named in the same sentence as PAK1 in open-access papers (continued):
Sharing a sentence is not in itself a finding about the gene and the disease.
intestinal tumors (3 papers, 2017 to 2022). "TLR4 activates the β-catenin signaling pathway and forms intestinal tumors, while PAK1 is associated with CRC progression and metastasis." (PMID 36406461, 2022). "Since the 10-week old APC∆14/+ mice had spleens of normal size and weight compared to APC+/+ mice, we chose to determine the effect of PAK1 KO on intestinal tumour development and splenic lymphocytes in 10-week old mice." (PMID 28629331, 2017). "Our results demonstrate for the first time that PAK1 depletion up-regulated the immune system while inhibiting intestinal tumour initiation and progression in APC∆14/+ mice." (PMID 28629331, 2017). "Taken together this evidence indicates an important role for PAK1 in the growth and survival of intestinal tumours in APC∆14/+ mice." (PMID 28629331, 2017). "The aim of this study was to investigate the effect of PAK1 depletion and inhibition on the immune system and on intestinal tumour formation in APC∆14/+ mice." (PMID 28629331, 2017). "Taken together our findings indicate that inhibition of PAK1 not only supresses intestinal tumour progression, but also stimulates the immune response by up-regulation of immune system." (PMID 28629331, 2017). "As the role of PAK1 in the immune response to tumours has not been reported previously, the aim of this study was to investigate the effect of modulation of PAK1 expression and activity on the immune response and the development of intestinal tumours in APC∆14/+ mice." (PMID 28629331, 2017). "We have previously shown that PAK1 expression and activity were increased, and positively correlated with the levels of HIF-1α and β-catenin, in intestinal tumours in APC∆14/+ mice." (PMID 28629331, 2017). "Depletion of PAK1 in APC∆14/+ mice increased the numbers of splenic T- and B- lymphocytes and decreased the numbers of intestinal tumours." (PMID 28629331, 2017). "Depletion of active PAK1 up-regulates the immune system of APC∆14/+ mice and suppresses intestinal tumour development." (PMID 28629331, 2017). "Taken together the data obtained from either PAK1 KO APC∆14/+ mice or PF-3758309-treated APC∆14/+ mice imply a more important role for PAK1 in the initiation of intestinal tumours rather than their subsequent growth." (PMID 28629331, 2017).
liver fibrosis (3 papers, 2016 to 2023). "PAK1, the most extensively studied PAKs, plays important roles in the occurrence of hepatitis and liver fibrosis through affecting hepatocytes, immune cells, and myofibroblasts." (PMID 36672500, 2023). "To investigate whether blocking PAK-1 function might improve liver fibrosis, we administered IPA3 intraperitoneally to mice during the last four weeks of an 8-week regime of CCl4 injections." (PMID 27535340, 2016).
mental disorder (3 papers, 2016 to 2023). A disease that has its basis in the disruption of mental process. "Pathogenic variations of PAK1, PAK2 and PAK3 are responsible for ID and/or psychiatric disorders, and are often associated with brain anomalies." (PMID 36937657, 2023). "Transcriptomic analysis and genome-wide association in schizophrenia and bipolar disorder identify PAK1 and PAK3 as the differentially expressed genes along with several other genes in the RAC1/CDC42 pathway, highlighting the role of this pathway in these psychiatric disorders." (PMID 36937657, 2023).
metastatic disease (3 papers, 2015 to 2021). "Our findings suggest that despite the presence of OS in the lymphohematogenous circulation, PAK1‐specific therapy may still have a potential clinical benefit by reducing the progression of pulmonary metastases and the development of the clinically overt metastatic disease." (PMID 31872963, 2020).
myocardial infarction (3 papers, 2014 to 2024). Gross necrosis of the myocardium, as a result of interruption of the blood supply to the area, as in coronary thrombosis. "By triggering Pak1/Akt signaling in myocardial infarction (MI), miR-665 knockdown reduces the buildup of ROS and apoptosis that are brought on by ischemia/reperfusion damage in cardiomyocytes." (PMID 38084332, 2023).
neuroblastoma (3 papers, 2016 to 2025). Neuroblastoma (NB) is the most common solid, extracranial childhood tumor. "Indeed, oxidative stress decreased the phosphorylation of PAK1 in neuroblastoma cells, cultured dopamine (DA) neurons, or rat midbrains." (PMID 27121078, 2016). "However, indirect targeting of p38, by blocking its upstream activator PAK1 with the drug IPA-3, inhibits TNT formation in a neuroblastoma cell line." (PMID 33003486, 2020).
Stroke (3 papers, 2007 to 2021). Sudden impairment of blood flow to a part of the brain due to occlusion or rupture of an artery to the brain. "RT-PCR confirmed the upregulation of pak1 determined by the microarrays in pooled samples from stroke patients who survived between 2 and 6 days following stroke." (PMID 17997827, 2007). "In patients surviving for 3 days to 4 weeks after stroke, increased PAK1 nuclear staining was seen in neurons in both peri-infarcted and infarcted regions (Figure 4Dii)." (PMID 17997827, 2007). "Moreover, findings indicate that Axl mediates the activation of the small GTPase Rac1, which improves post-stroke recovery and angiogenesis mediated by Pak1." (PMID 34074054, 2021). "Based on existing evidence that Rac1 improves stroke symptoms through Pak1 signaling, the role of Pak1 in autophagy initiation might be through Axl." (PMID 34074054, 2021). "Amongst these genes we examined in more detail a small subset with no prior report of a role in stroke (PAK1, MMP11 and INI1)." (PMID 17997827, 2007). "Using Western blotting and immunohistochemistry, PAK1, INI1 and MMP11 protein expression and localization was determined in the contralateral and ipsilateral brain areas of individual stroke patients and rats subjected to MCAO, and in HBMEC and HFN exposed to OGD and reperfusion." (PMID 17997827, 2007).
acute lymphoblastic leukemia (2 papers, 2016 to 2021). Leukemia with an acute onset, characterized by the presence of lymphoblasts in the bone marrow and the peripheral blood. "miR- 101 has been described to be a pro-apoptotic factor in childhood acute lymphoblastic leukemia and miR-7 as an tumor suppressor inhibiting various receptor tyrosine kinases such as EGFR, IGF-1R and p21 activated kinase (PAK1)." (PMID 27542283, 2016).
acute megakaryoblastic leukemia (2 papers, 2022 to 2024). Acute megakaryoblastic leukemia (AMKL) is a form of acute myeloid leukemia (AML) that occurs predominantly in childhood and particularly in children with Down syndrome (DS-AMKL). "Meanwhile, in acute megakaryoblastic leukemia (AMKL), p21-activated kinase 1 (PAK1) is significantly enriched." (PMID 39055650, 2024).
Arthritis (2 papers, 2015 to 2021). Inflammation of a joint. "Rather, it appears to drive further (arthritis-associated) epigenetic changes, such as the Promoter3K hypermethylation (silencing) of PAK1, a kinase identified as a key driver of SF migration and invasion in RA and one of our Binary Signature genes." (PMID 34748611, 2021).
atrial fibrillation (2 papers, 2023 to 2025). A disorder characterized by an electrocardiographic finding of a supraventricular arrhythmia characterized by the replacement of consistent P waves by rapid oscillations or fibrillatory waves that vary in size, shape and timing and are accompanied by an irregular ventricular response. "Pak1 cKO mice show atrial arrhythmias including atrial fibrillation (AF) in vivo, detected during anaesthetized electrocardiography without evidence of interstitial fibrosis upon Masson's trichrome staining." (PMID 37122217, 2023). "Studies by Banach and colleagues (2014, 2018, 2023) on the role of Pak1 activity as a factor in SAN dysfunction and atrial fibrillation (AF) focused on the effect of loss of activity of Pak1 to result in an increase in the activity of NADPH oxidase 2 (NOX2) to generate reactive oxygen species (ROS)." (PMID 40065530, 2025).
cholangiocarcinoma (2 papers, 2022 to 2023). A carcinoma that arises from the intrahepatic biliary tree (intrahepatic cholangiocarcinoma) or from the junction, or adjacent to the junction, of the right and left hepatic ducts (hilar cholangiocarcinoma). "For instance, PAK1 has been reported to increase pemigatinib resistance in cholangiocarcinoma through β-catenin/Smad4-mediated pathways." (PMID 37537668, 2023). "The role of PAK1 in the activation of β-catenin signalling may also contribute to Sorafenib resistance, as reported for pemigatinib resistance in cholangiocarcinoma." (PMID 37537668, 2023).
chronic lymphocytic leukaemia (2 papers, 2022 to 2023). "PAK1 is upregulated in chronic lymphocytic leukemia (CLL), and high levels of PAK1 are correlated with a poor prognosis." (PMID 36830998, 2023).
cognitive deficits (2 papers, 2017 to 2025). "PAK1 activation through autosomal dominant gain‐of‐function mutations causes neurodevelopmental disorders with cognitive impairment." (PMID 41451871, 2025). "As such, the PAK1-3-related cascades are of particular interest due to their potential causal role in cognitive deficits in AD, but also in mental retardation." (PMID 28522792, 2017).
Fanconi anemia (2 papers, 2016 to 2021). Fanconi anemia (FA) is a hereditary DNA repair disorder characterized by progressive pancytopenia with bone marrow failure, variable congenital malformations and predisposition to develop hematological or solid tumors. "PAK1 is also implicated in the activation of the microrchidia CW-type zinc finger 2 (MORC2) and Fanconi anemia (FA)/BRCA pathways, suggesting an important role of PAK1 in chromatin remodeling and DSB repair." (PMID 33546351, 2021).
lymphopenia (2 papers, 2018 to 2023). Reduction in the number of lymphocytes. "We also observed that lymphopenia was temporally associated with the upregulation of CCR2, LYN, PAK1, PTK2B, SRC, STAT3, which are involved in the chemokine signaling pathway." (PMID 30713538, 2018).
mucosal melanoma (2 papers, 2022 to 2024). A melanoma that arises from a mucosal site. "In addition to sharing similar recurrently affected genes, acral and mucosal melanomas also shared the most recurrently altered TAD boundary (chr11:77750000–77825000), which is adjacent to the TADs containing PAK1 and GAB2." (PMID 38758740, 2024).
Oral Squamous Cell Carcinoma (2 papers, 2016 to 2020). "Stimulation of Oral Squamous Cell Carcinoma (OSCC) cells with serum growth factors leads to PAK1 re-localization and might cause a profound cytoskeletal remodelling." (PMID 27229476, 2016).
Salmonella Infections (2 papers, 2021 to 2023). Infections with bacteria of the genus SALMONELLA. "In the AOM/DSS mouse model, lower CDC42 K153 acetylation caused by Salmonella infection is associated with higher PAK1 phosphorylation but lower PAK4 phosphorylation." (PMID 36812247, 2023). "The results of western blot assay showed that PAK4 phosphorylation level appeared to be lower in the AOM/DSS-treated mice group with Salmonella infection than in the uninfected mice group, whereas PAK1 phosphorylation level showed the opposite trend." (PMID 36812247, 2023). "More recent research has demonstrated that PAK1 activated during Salmonella infection plays a vital role in the stimulation of NF-κB, in order to establish pro-inflammatory signalling after cell invasion." (PMID 34460869, 2021). "Our results showed that the acetylation of CDC42 has little effect on the binding of PAK1, but the regulatory mechanism in the AOM/DSS induced CRC model with Salmonella infection is highly complicated, so other factors might enhance phosphorylation of PAK1 besides CDC42." (PMID 36812247, 2023).
sarcoma (2 papers, 2020 to 2021). A usually aggressive malignant neoplasm of the soft tissue or bone. "miR-130b enhanced the malignant phenotype of ewing sarcoma cells by activating the CDC42/PAK1 signaling pathway." (PMID 34289832, 2021).
squamous non-small cell lung cancer (2 papers, 2014 to 2019). "Furthermore, strong nuclear and cytoplasmic PAK1 expression was also prevalent in squamous non-small cell lung carcinomas, and selective PAK1 inhibition was associated with delayed cell cycle progression in vitro and in vivo." (PMID 25182632, 2014).
steatosis (2 papers, 2018 to 2022). Increased lipid within the cytoplasm of cells. "On the other hand, in the presence of steatosis, the abolishment of NRG1 or PAK1 effects affected IGF1 since in steatotic livers from the BD+anti-NRG1+LT and BD+anti-PAK1+LT groups, IGF1 levels were lower than in the BD+LT group." (PMID 35625715, 2022). "The inhibition of either NRG1 or PAK1 (BD+anti-NRG1+LT and BD+anti-PAK1+LT groups) decreased VEGFA in non-steatotic livers, while no changes were observed in the presence of steatosis when compared with the results obtained in the BD+LT group." (PMID 35625715, 2022).
ulcerative colitis (2 papers, 2018 to 2020). An inflammatory bowel disease involving the mucosal surface of the large intestine and rectum. "Neurexophilin and PC-Esterase Domain Family, Member 4 (NXPE4), which has biased expression in colon, is potentially associated with ulcerative colitis, as is P21 activated protein kinase 1 (PAK1)." (PMID 33308304, 2020). "Mesalamine, the first line treatment for chronic inflammation in ulcerative colitis, was recently established as a PAK1 inhibitor, and others have shown it is a PPARγ ligand." (PMID 31011108, 2018).
amyloid (1 paper, 2025). "Importantly, in vivo studies demonstrated that oral administration of NVS‐PAK1‐1 effectively inhibited PAK1 activity and prevented spine density loss in 5xFAD female mice without altering amyloid pathology." (PMID 41451871, 2025).
anaplastic thyroid cancer (1 paper, 2019). "Further, we evaluated the effect of inhibiting PAK1 on anaplastic thyroid cancer cells by treating 8505C cells with a PAK1 inhibitor IPA-3." (PMID 31905765, 2019). "Since, IPA-3 selectively inhibits PAK1 and does not cause inhibition of groups II PAKs (including PAK4), these results suggest that while targeting PAK4 in anaplastic thyroid cancer cells is a viable option, targeting PAK1 is not." (PMID 31905765, 2019).
autoimmune hepatitis (1 paper, 2023). Hepatitis caused by autoantibodies. "Increased PAK1 expression in Kupffer cells was also noticed in patients with autoimmune hepatitis, and the PAK1 expression was found to be associated with disease progression." (PMID 36672500, 2023). "Alteration of PAK1 in Kupffer cells in autoimmune hepatitis implicates the potential immune regulation of PAK in liver diseases." (PMID 36672500, 2023).
benign meningioma (1 paper, 2015). A grade I, slowly growing meningioma. "Similar results were observed in an NF2-deficient benign meningioma cell line, Ben-Men1-LucB, hereafter referred to as Ben-Men, in which expression level diminished by 54% and 58% for Pak1 and Pak2, respectively." (PMID 25596744, 2015).
brain tumors (1 paper, 2019). "Using MR image analysis at day 28, brain tumor size was quantified and it was found that brain tumors present in mice injected with PAK1 knockdown cells were significantly smaller (0.05 ± 0.01 mm3) than control tumors (0.10 ± 0.02 mm3) (p = 0.015)." (PMID 30651600, 2019). "Histological quantification of brain tumor burden was performed and a significant reduction in tumor burden was found in mice with PAK1 knockdown cells compared to control (p = 0.04)." (PMID 30651600, 2019).
choriocarcinoma (1 paper, 2015). An aggressive malignant tumor arising from trophoblastic cells. "We also revealed overexpression of Pak1 in choriocarcinoma and hydatidiform moles that progressed to aggressive disease." (PMID 26218748, 2015).
chronic heart failure (1 paper, 2023). "The activities of PRKAA1, PRKACA, and PAK1 were significantly enhanced in post-infarction chronic heart failure." (PMID 37405054, 2023). "Expression levels of PRKAA1, PRKACA, and PAK1 were increased in post-infarction chronic heart failure rats." (PMID 37405054, 2023). "PRKAA1, PRKACA, and PAK1 might serve as potential therapeutic targets for post-infarction chronic heart failure." (PMID 37405054, 2023).
colorectal adenoma (1 paper, 2013). An adenoma that arises from the colon or rectum. "Moreover, PAK1 expression levels are significantly lower in normal colon tissue than in colorectal adenomas and invasive neoplasms." (PMID 24236193, 2013).
colorectal tumor (1 paper, 2013). "Similarly, PAK1 expression in colorectal tumor tissue is associated with LN status, distant metastasis and tumor stages." (PMID 24236193, 2013).
congenital myopathies (1 paper, 2019). "The development of skeletal muscle disease in dKO mice raises the possibility that mutations in PAK1 and/or PAK2 may underlie human dystrophies or congenital myopathies." (PMID 30791960, 2019).
cutaneous melanoma (1 paper, 2023). A primary melanoma arising from atypical melanocytes in the skin. "In a small subset of cutaneous melanomas, and in the vast majority of uveal melanomas, the activation of PAK1 is expected as a consequence of activating mutations in the GNAQ and GNA11 oncogenes, which reportedly signal through RAC1 and RAS." (PMID 37830586, 2023). "The co-occurrence of several mutations that are potentially capable of activating PAK1 is not uncommon in cutaneous melanoma." (PMID 37830586, 2023). "The hyperactivation of PAK1 in cutaneous melanomas may be further attributed to activating mutations in RAC1, but also to even more common activating mutations in NRAS and the inactivation of RAS inhibitor NF1, as RAS-induced transformation involves and depends on the activation of RAC1 and PAK1." (PMID 37830586, 2023).
demyelinating (1 paper, 2025). "To determine if PAK1-regulated OPC behavior is preserved in demyelinating disorders, we leveraged the well-established focal demyelination mouse model of lysolecithin in which both OLs and OPCs are depleted in the lesional area." (PMID 40586933, 2025). "The current study aimed to define if and how PAK1 dysregulation affects early postnatal OPC development and to determine if PAK1 controls OPC proliferation and repopulation in demyelinating lesions." (PMID 40586933, 2025). "Taken together, our genetic evidence demonstrated that PAK1’s kinase activity is essential for OPC proliferation and repopulation in demyelination lesions in response to white matter injury." (PMID 40586933, 2025).
Dyskinesia (1 paper, 2024). A movement disorder which consists of effects including diminished voluntary movements and the presence of involuntary movements. "However, the MAPK pathway activator PAK1 was downregulated in the indirect pathway and upregulated in the direct pathway, strongly suggesting a role for PAK1 in regulating the opposing effects of LDOPA on these two pathways in dyskinesia." (PMID 40144773, 2024).
E. coli infection (1 paper, 2021). "PAK1 also regulates NLRP3 at Thr659 during E. coli infection, suggesting PAK1 regulates multiple inflammasome proteins during bacterial infection." (PMID 34854899, 2021).
endometrioid carcinoma (1 paper, 2015). "Pak1 enhance endometrial cancer cell proliferation particular in type I endometrioid carcinoma." (PMID 26218748, 2015). "We demonstrated significantly higher Pak1 expression in Type I endometrioid carcinoma than Type II non-endometrioid carcinoma." (PMID 26218748, 2015). "Moreover, type I endometrioid carcinomas showed significantly higher Pak1 expression than type II non-endometrioid carcinomas (P<0.001)." (PMID 26218748, 2015).
Esophageal Small Cell Carcinoma (1 paper, 2015). "Correlation between PAK1 overexpression and clinicopathological variables in primary esophageal small cell carcinoma." (PMID 26023713, 2015).